DLK1 (delta like non-canonical Notch ligand 1)
Diseases named in the same sentence as DLK1 in open-access papers (continued):
Sharing a sentence is not in itself a finding about the gene and the disease.
lung carcinoma (19 papers, 2006 to 2024). "In our previous studies, we found that up-regulated DLK1 expression is associated with lung cancer cell invasion through activating Notch signaling." (PMID 31661545, 2019). "We discovered that Snail mediated the downregulation of the imprinted Dlk1-Dio3 locus, a complex genomic region containing protein-coding genes and non-coding RNAs that has been linked to tumor malignancy in lung cancer patients." (PMID 30190790, 2018). "We found that the DLK1-promoted invasion of lung cancer cells was associated with upregulation of MMP9 expression and its extracellular activity, which are involved in ECM breakdown and highly associated with tumor invasion." (PMID 24621612, 2014). "DLK1 has also been found to be expressed in lung cancer, pancreatic cancer, ovarian cancer, endocrine cancer, and pediatric cancer." (PMID 39769389, 2024). "DLK1 is known to affect MMP9 expression levels through NOTCH signaling to promote lung cancer cell invasion." (PMID 35163478, 2022). "In conclusion, we verified the nuclear localization of DLK1 in lung cancer cells, for which there was a prior reason to expect." (PMID 31661545, 2019). "To substantiate the observation, we examined the cellular localization of endogenous DLK1 in lung cancer cell lines." (PMID 31661545, 2019). "Through nuclear fraction extraction or in situ immunofluorescent labeling, we confirmed with the nuclear localization of DLK1 in lung cancer cell lines." (PMID 31661545, 2019). "Intriguingly, the expression of several Dlk1-Dio3 locus genes was downregulated in the splenocytes following culture with CM from Snail-expressing murine or human lung cancer cells." (PMID 30190790, 2018). "DLK1 has been reported aberrantly expressed in various types of tumors, such as hepatocellular carcinoma, glioma, renal cell carcinoma and lung cancer." (PMID 29435111, 2018). "The study that we present here provides evidence suggesting that DLK1 enhanced the ability of lung cancer cells to invade the extracellular matrix (ECM), which validated our previous gene expression profiling results derived from microarray analysis." (PMID 24621612, 2014). "Aberrant expression of DLK1 has been found in various types of human cancers, including lung cancer." (PMID 24621612, 2014). "A cell model that stably expressed exogenous dlk1 was established following that the dlk1 gene was cloned into a eukaryotic expression vector and then transfected into the lung cancer cells H520." (PMID 20959062, 2010). "Notably, DLK1 exhibits elevated expression levels in numerous common malignancies, including liver, breast, brain, pancreas, colon, and lung cancers, as well as endocrine-related cancers such as ovarian tumors and pheochromocytoma." (PMID 39595993, 2024). "The nuclear localization of DLK1 in our data revealed great clinical significance for lung cancer." (PMID 31661545, 2019). "In the present study, we verified the nuclear localization of DLK1 in lung cancer cells." (PMID 31661545, 2019). "We therefore hypothesized that a soluble factor secreted by Snail-expressing lung cancer cells likewise mediates the Dlk1-Dio3 locus repression in immune cells." (PMID 30190790, 2018). "Elevated expression of DLK1 was reported in neuroblastoma from patients with poor outcome and induction of DLK1 expression in lung cancer activated both notch-dependent signaling and upregulated matrix metalloproteinase MMP9, which increased cellular invasive potential." (PMID 28871274, 2017). "It is tempting to speculate that the aberrant DLK1 intronic RNA expression may have a role in lung cancer progression." (PMID 26805894, 2016). "An analysis of NOTCH1 and HES1 gene expression and Notch intracellular domain (NICD) nuclear translocation during DLK1 stimulation or depletion demonstrated that DLK1 could activate Notch signaling in lung cancer cells." (PMID 24621612, 2014).
lung carcinoma (continued). "Our findings showed that a mixture of membrane and secreted DLK1 might activate Notch signaling in human lung cancer cells." (PMID 24621612, 2014). "A same trend was also observed when DLK1 was overexpressed in another lung cancer cell line H1299." (PMID 24621612, 2014). "The Overexpression of dlk1 could accelerate the proliferation of lung cancer cells H520 in vitro, probably through up-regulating the expression of cell cycle protein CyclinB1." (PMID 20959062, 2010). "The imprinted gene dlk1 has been recognized as a cancer related gene since it aberrantly expressed in a series of cancer tissues, but its role in lung cancer is still unknown." (PMID 20959062, 2010). "In the present study, we validated that overexpression of DLK1 could enhance the invasive ability of lung cancer cells, which is consistent with our earlier findings derived from gene expression profiling and extends our knowledge of dlk1's function in human cancer." (PMID 24621612, 2014). "The aim of this study is to examine dlk1's expression in non-small cell lung cancers (NSCLCs) and investigate the molecular mechanism by which dlk1 could accelerate the proliferation of the cells in lung cancer cell lines (H520)." (PMID 20959062, 2010). "Patients with lung cancer showed three deregulated protein-coding genes: one was hypermethylated (DIO3) and two were hypomethylated (DLK1 and RTL1)." (PMID 29435111, 2018). "RT-PCR validation of expression of introns of DLK1 and LRG1, lung cancer genes verified the results of the bioinformatic analyses." (PMID 26805894, 2016). "Using RT-PCRs, we validated the expression of introns of two oncogenes, DLK1 and LRG1, known to be key players in lung cancer progression, and demonstrate changed intronic expression with supplement treatment in cancer cells." (PMID 26805894, 2016). "Furthermore, we experimentally validate the expression of introns of two oncogenes, DLK1 and LRG1, which are major players in lung cancer progression." (PMID 26805894, 2016). "The data presented in this study suggest that DLK1 can promote the invasion of lung cancer cells by upregulating MMP9 expression, which depends on Notch signaling." (PMID 24621612, 2014). "Among others, these include CASP9 and CDC42 (1p36), which have already been studied in neuroblastoma; CACNA2D3 (3p21-p22), which was recently proposed as a tumor suppressor gene in lung cancer; IGSF4 (11q23), which is a known tumor suppressor gene in several cancers; and DLK1 (14q)." (PMID 16989664, 2006).
neuroblastoma (17 papers, 2005 to 2026). Neuroblastoma (NB) is the most common solid, extracranial childhood tumor. "Analysis of DLK1 allelic expression in the informative SK-N-AS neuroblastoma line demonstrated monoallelic (allele C) DLK1 expression pre- and post-treatment with 5-AzaC." (PMID 15798773, 2005). "A Phase 1 first-in-human DLK1-directed immunotherapy clinical trial to treat neuroendocrine neoplasms, including neuroblastoma, in adult patients is currently open (ClinicalTrials.gov: NCT06041516)." (PMID 39932005, 2025). "Further studies have shown that depletion of DLK1 in neuroblastoma cells promotes cell differentiation." (PMID 40104501, 2025). "Recent research has identified DLK1 as a promising target for immunotherapy, particularly in neuroblastoma." (PMID 40104501, 2025). "DLK1 is overexpressed in neuroblastoma cells, and its expression is largely restricted to the adrenal medulla and pituitary gland." (PMID 40104501, 2025). "DLK1, also known as preadipocyte factor 1 (Pref-1), was first discovered in neuroblastoma because of its inhibitory effect on preadipocyte differentiation." (PMID 35739860, 2022). "Other strongly upregulated genes in this set were Dlk1, highly expressed in early sympathetic neuron progenitors and Plk1, a known therapeutic target in neuroblastoma." (PMID 34638267, 2021). "β-carotene treatment strongly reduces cell growth and induces neuronal differentiation along with downregulation of DLK1 in neuroblastoma CSCs." (PMID 31191243, 2019). "Serial analysis of gene expression-analysis in a neuroblastoma cell line revealed another of our identified targets, DLK-1, to be highly upregulated." (PMID 28871274, 2017). "It has been demonstrated that Plagl1 re-expression in a neuroblastoma cell line induces several imprinted genes, including Dlk1." (PMID 18989361, 2008). "DLK1, on the other hand, is expressed to a lesser degree in the unfavorable neuroblastoma than in the favorable tumors and the neuroblast (in concordance with observations reported by Hsiao and coworkers)." (PMID 16989664, 2006). "We investigated neuroblastoma and phaeochromocytoma as DLK1 is highly expressed in the adrenal medulla." (PMID 15798773, 2005). "Additionally, ADCT-701, an antibody-drug conjugate currently in an ongoing phase I clinical trial (NCT06041516) for adult patients with neuroendocrine tumors, has demonstrated effectiveness in targeting and killing DLK1-positive neuroblastoma cells in vivo." (PMID 40104501, 2025). "DLK1 may play a role in maintaining the undifferentiated state of neuroblastoma cells, preventing their maturation." (PMID 40104501, 2025). "Furthermore, we review recent evidence supporting roles for DLK1 in the maintenance of aggressive stem cell characteristics of tumor cells, specifically focusing on central nervous system tumors, neuroblastoma, and hepatocellular carcinoma." (PMID 34606325, 2022). "DLK1 (delta drosophila homolog-like 1 or delta-like 1 homologue) first discovered in the neuroblastoma could inhibit the differentiation of pre-adipocytes and was known as pre-adipocyte factor-1 (pref-1)." (PMID 29771917, 2018). "In addition, the three neuroblastoma cell lines with 5′ GTL2 DMR hypermethylation (but uninformative for DLK1 imprinting status) showed almost complete methylation at all IG-DMR CpGs analysed." (PMID 15798773, 2005). "Interestingly, the combination of retinoic acid and the knockdown of DLK1 was found to induce the differentiation of neuroblastoma cells in vitro better than either intervention on its own, highlighting the tumorigenicity of DLK1 in neuroblastoma." (PMID 28871274, 2017). "Notably, DLK1 is consistently re-expressed across a broad range of malignancies, with the highest prevalence observed in endocrine and neuroendocrine tumours, including adrenocortical carcinoma, phaeochromocytoma/paraganglioma, medullary thyroid carcinoma, and neuroblastoma." (PMID 42023826, 2026).
neuroblastoma (continued). "We also analysed DLK1 and GTL2 expression before and after treatment with the demethylating agent 5-azacytidine (5-AzaC) in the four neuroblastoma cell lines with GTL2 promoter DMR hypermethylation." (PMID 15798773, 2005).
Insulin resistance (16 papers, 2007 to 2024). Increased resistance towards insulin, that is, diminished effectiveness of insulin in reducing blood glucose levels. "Paternally transmitted foetal DLK1 genotype affected maternal DLK1 levels that were positively associated with insulin-resistance and inversely correlated with insulin secretion during the third trimester of pregnancy." (PMID 36568069, 2022). "Maternal serum DLK1 concentration ranks were also positively associated with indices of insulin resistance (C-peptide derived HOMA of Insulin Resistance [HOMA IR]: P = 0.01, and fasting C-peptide concentration: P = 5.6 × 10-3)." (PMID 33640968, 2021). "In our study, we evaluated the concentrations of DLK1 and nesfatin-1, which are closely related to insulin resistance, in pregnant women with GDM and their association with metabolic parameters." (PMID 34540403, 2021). "In another study of middle-aged men, serum DLK1 concentrations were also positively associated with insulin resistance as assessed in intravenous glucose tolerance test studies." (PMID 33640968, 2021). "Likewise, we also considered that GDM, which is based on insulin resistance, might be associated with DLK1, and we determined a positive correlation between DLK1 levels and HOMA-IR among patients with GDM." (PMID 34540403, 2021). "Although we report a weak correlation with insulin resistance, this finding would suggest a DLK1-mediated metabolic effect." (PMID 36568069, 2022). "We sought associations with parental transmission of DLK1 polymorphisms, pregnancy outcomes (GDM and gestational hypertension), markers of insulin resistance and secretion derived from an oral glucose tolerance test (OGTT), and offspring size at birth." (PMID 33640968, 2021). "Ultimately, more detailed studies are needed in vivo and in vitro to unveil the relationship of DLK1 with insulin resistance." (PMID 34540403, 2021). "The data would be consistent with the possibility of DLK1 having a role in the development of insulin resistance of pregnancy combined with stimulating compensatory hyperinsulinemia." (PMID 33640968, 2021). "Transgenic mice overexpressing Dlk1 from an adipose-specific promoter exhibit reduced adipose mass, impaired glucose tolerance and decreased insulin resistance." (PMID 25551289, 2014). "There are no published studies of glucose or insulin tolerance in Dlk1 knockout mice, but transgenic mice overexpressing Dlk1 exhibit reduced adipose deposition, glucose intolerance and insulin resistance." (PMID 25551289, 2014). "Moreover, data about correlation between Dlk1 levels and both body fat percentage and insulin resistance are conflicting." (PMID 36568069, 2022). "In a recently published study of 68-year-old men, circulating DLK1 concentrations were positively correlated with insulin resistance measured by euglycemic hyperinsulinemic clamps and HOMA IR, as well as being negatively associated with muscular glucose disposal rates." (PMID 33640968, 2021). "An alternative explanation for our observed associations, although inconsistent with our genetic data, is that first-trimester insulin resistance, leading to hyperinsulinemia, may have resulted in increased placental size and therefore DLK1 secretion." (PMID 33640968, 2021). "The associations that we found between maternal serum DLK1 concentrations in pregnancy and markers of insulin resistance (HOMA IR and fasting C-peptide concentrations) have not been reported previously." (PMID 33640968, 2021). "Findings that both DLK1-null and DLK1-overexpressing transgenic mice develop insulin resistance and glucose intolerance also indicate that proper development of adipose tissue function might be critical for maintaining glucose/insulin homeostasis." (PMID 34540403, 2021). "However, there are some data from men linking DLK1 concentrations to insulin resistance." (PMID 33640968, 2021).
Insulin resistance (continued). "The mechanism of the association between circulating DLK1 concentrations and gestational hypertension is unknown, although our data (not shown) suggest that it is independent of insulin resistance." (PMID 33640968, 2021). "Dlk1-deficient mice exhibit an obese phenotype associated with changes in serum lipids, while Dlk1-overexpressing mice with high serum levels of FA1 display a decreased fat mass, a phenotype reminiscent of lipodystrophy, decreased glucose tolerance, and insulin resistance." (PMID 22844611, 2012).
hepatocellular carcinoma (15 papers, 2012 to 2025). A malignant tumor that arises from hepatocytes. "In particular, DLK1 overexpression has been associated with increased aggressiveness and poor outcome in glioblastoma (GBM), hepatocellular carcinoma, ovarian, prostate, and lung cancer." (PMID 34606325, 2022). "The 14q32 domain, also named Dlk1-Gtl2 in mice and Dlk-Dio3 in humans, plays an important role in many cancers, including melanoma, osteosarcoma, hepatocellular carcinoma, gastric cancer, ovarian cancer, and glioma." (PMID 33324542, 2020). "DLK1 was also found aberrantly expressed in other human cancers, including hepatocellular carcinoma (HCC), breast cancer (BC), acute myeloid leukemia (AML) and so on." (PMID 31661545, 2019). "Indeed, DLK1-directed CAR T cells have been shown to have pre-clinical efficacy among DLK1-expressing hepatocellular carcinoma models." (PMID 39416174, 2024). "Given that miR-379 could suppress the IGF1/IGF1R and PI3K/AKT signaling pathway in hepatocellular carcinoma, and DLK1 is the potential target gene of miR-329 that may be involved in IGF1 signaling and muscle growth through Akt phosphorylation." (PMID 34527673, 2021). "Many studies demonstrate that expression of DLK1 is elevated in a wide range of tumor types, including neuroblastoma, gliomas, breast cancer, colon cancer, pancreatic cancer, small-cell lung carcinoma, leukemia and hepatocellular carcinoma." (PMID 27683116, 2016). "Serum AFP is a widely used hepatocellular carcinoma (HCC) biomarker and, in the Afphi branch 1, we identified an intermediate cellular state, largely corresponding to the Dlk1+/Gpc3+ ‘hepatoblastic cluster’ (bottom)." (PMID 39112713, 2024). "We previously showed that Delta-like homolog 1 (DLK1) may be a therapeutic target against the CSCs of human hepatocellular carcinoma (HCC)." (PMID 27683116, 2016). "For example, Dupuy and colleagues performed a SB-mediated hepatocellular carcinoma (HCC) screen and found frequent insertions in the complex imprinted Dlk1-Dio3 locus." (PMID 26481584, 2015). "Delta-like 1 homolog (DLK1), a non-canonical Notch ligand, is highly expressed in various malignant tumors, especially in hepatocellular carcinoma (HCC)." (PMID 39769389, 2024).